BARX1 (BARX homeobox 1)
Description:
Transcription factor, which is involved in craniofacial development, in odontogenesis and in stomach organogenesis. May have a role in the differentiation of molars from incisors. Plays a role in suppressing endodermal Wnt activity (By similarity). Binds to a regulatory module of the NCAM promoter.
Tractability: No criterion of Open Targets' tractability assessment is met for any kind of drug.
Gene: Protein-coding gene on chromosome 9 (93,951,627 to 93,955,355, reverse strand). Ensembl gene ENSG00000131668.
Subcellular location: Nucleus
Subcellular location (Human Protein Atlas): Nucleoplasm; Vesicles
Gene Ontology:
Molecular function: DNA-binding transcription factor activity; DNA-binding transcription factor activity, RNA polymerase II-specific; RNA polymerase II transcription regulatory region sequence-specific DNA binding; DNA binding
Biological process: regulation of transcription by RNA polymerase II; regulation of DNA-templated transcription
Cellular component: chromatin; nucleus
Genetic constraint (gnomAD): Loss-of-function variants: 12 observed, 15.36 expected, observed/expected ratio (o/e) 0.78, 90% interval 0.5 to 1.27. The synonymous counts are far from expectation, so gnomAD's model fits this gene poorly and the ratio says little. Missense variants: 309 observed, 265.13 expected, observed/expected ratio (o/e) 1.17, 90% interval 1.06 to 1.28. Synonymous variants: 177 observed, 126.34 expected, observed/expected ratio (o/e) 1.4, 90% interval 1.24 to 1.59.
Homologues: Orthologues: chimpanzee BARX1 (100% identical), macaque BARX1 (99% identical), pig BARX1 (96% identical), rat Barx1 (96% identical), mouse Barx1 (95% identical), dog BARX1 (94% identical), guinea pig BARX1 (78% identical), rabbit BARX1 (74% identical), zebrafish barx1 (66% identical), tropical clawed frog barx1 (62% identical), Drosophila melanogaster B-H1 (22% identical), Drosophila melanogaster B-H2 (22% identical), and 2 more. Paralogues in human: BARX2 (42% identical), BARHL2 (28% identical), BARHL1 (28% identical).
Diseases named in the same sentence as BARX1 in open-access papers:
BARX1 is named in the same sentence as 34 diseases in open-access papers, as found by Europe PMC text mining. Sharing a sentence is not in itself a finding about the gene and the disease. The quoted sentences say what the papers report.
clear cell renal cell carcinoma (5 papers, 2021 to 2023). "Increased BARX1 activity has been associated with enhanced cell proliferation and migration activity within pathological tissue like clear cell renal cell carcinoma." (PMID 37733420, 2022). "BARX1 encodes a transcription factor linked to poor prognosis and may promote clear cell renal cell carcinoma (ccRCC) proliferation and migration." (PMID 36353226, 2022). "Most recent studies have revealed that BARX1 was highly expressed and played an oncogenic role in endometrial carcinoma (EC) and clear cell renal cell carcinoma (ccRCC) tissues." (PMID 37587140, 2023). "Likewise, bioinformatics algorithm and differentially expressed TFs’ analysis show that BARX1, as well as DLX4, play an oncogenic role in clear cell renal cell carcinoma (ccRCC) by promoting proliferation and epithelial–mesenchymal transition." (PMID 37587140, 2023).
hepatocellular carcinoma (5 papers, 2017 to 2023). A malignant tumor that arises from hepatocytes. "Notably, BARX1 expression is decreased in hepatocellular carcinoma (HCC), and its absence causes enhancement of tumour invasion and metastasis by inducing MGAT5 and MMP9 expression." (PMID 36927457, 2023). "One study showed that BARX1 was notably downregulated in human hepatocellular carcinoma (HCC) tissues, which was correlated with poor prognosis." (PMID 37587140, 2023). "BARX homeobox 1 (BARX1), a transcription factor, is involved in craniofacial development and in hepatocellular carcinoma metastasis." (PMID 35592316, 2022).
colorectal cancer (3 papers, 2017 to 2021). A primary or metastatic malignant neoplasm that affects the colon or rectum. "In these, 8 SNPs were annotated to the same gene in pairs of height- and colorectal cancer risk-associated SNPs, leading to the following four gene annotations: BMP2, PITX1, DCBLD1, and BARX1." (PMID 28117334, 2017). "Interestingly, Barx1 gene promoter was hypermethylated in human colorectal cancer and gastric cancer, and Barx1 expression was lower in cancer tissues than adjacent noncancer tissues." (PMID 29069753, 2017).
cleft palate (2 papers, 2010 to 2022). Cleft palate is a fissure type embryopathy that affects the soft and hard palate to varying degrees. "Mice carrying a large deletion of chromosome 14 (Pub36-/-), a region that contains the Spry2 gene exhibit cleft palate, excessive cell proliferation and up regulation of FGF target genes including Msx1, Etv5 and Barx1." (PMID 20459789, 2010). "Median values of semiquantitative evaluation for BARX1, DLX4, FOXE1, HOXB3, and MSX2 immunoreactivity within the control tissue group, unilateral cleft lip tissue group, bilateral cleft lip tissue group, and cleft palate tissue group." (PMID 37733420, 2022). "In the cleft palate affected tissue group, the median number of BARX1 positive epitheliocytes was no positive cells and no BARX1 positive epitheliocytes were found in any slide of the cleft palate affected tissue group." (PMID 37733420, 2022).
gastrointestinal stromal tumor (2 papers, 2022). "In gastrointestinal stromal tumors, BARX1 acts as a transcriptional and anatomical determinant of malignancy." (PMID 36353226, 2022). "BARX1 was hypermethylated in some patients with CRC, and its expression was a predictor of relapse-free survival for gastrointestinal stromal tumors." (PMID 35847938, 2022).
microstomia (2 papers, 2018 to 2020). "Moreover, the microdeletion of BARX1 in humans is associated with craniofacial developmental disorders such as microstomia and mandibular retrusion, while BARX1 was recently shown to function as a direct downstream factor of GATA4 in neural crest development." (PMID 32571211, 2020). "Microdeletion of the Barx1 gene in the human chromosome 9q22.32 is related to craniofacial developmental disorders such as microstomia deformity (small mouth) and mandibular retrusion." (PMID 29523871, 2018).
allergic rhinitis (1 paper, 2023). Inflammation of the nasal mucous membranes caused by an IgE-mediated response to external allergens. "Although a recent study showed that silencing BARX1 resulted in downregulated production of interleukins in allergic rhinitis-derived nasal fibroblasts, the exact role of BARX1 in tumor immune response remains to be elucidated." (PMID 37587140, 2023).
cleft lip (1 paper, 2022). Congenital defect in the upper lip where the maxillary prominence fails to merge with the merged medial nasal prominences. "This test revealed a statistically significant difference in the number of BARX1 immunopositive connective tissue cells between the controls and the bilateral cleft lip tissue group (U=12.0, p=0.046)." (PMID 37733420, 2022). "This test revealed a statistically significant difference in the number of BARX1 immunopositive connective tissue cells between the controls and the unilateral cleft lip tissue group (U=12.0, p=0.001)." (PMID 37733420, 2022). "The presence of BARX1 in postnatal mucosal connective tissue which mainly develop from the orofacial ectomesenchyme could indicate a possible involvement and interaction of BARX1 with the formation of unilateral and bilateral cleft lip." (PMID 37733420, 2022). "FOXE1 and BARX1 could be involved with both unilateral and bilateral cleft lip morphopathogenesis." (PMID 37733420, 2022). "While evaluating the number of BARX1 positive cells statistically significant differences were found between the control connective tissues and unilateral cleft lip connective tissues and between the control connective tissues and the bilateral cleft lip connective tissues." (PMID 37733420, 2022). "Transcription factors BARX1, FOXE1 are probably involved with the formation of both unilateral cleft lip and bilateral cleft lip morphopathogenesis processes within the postnatal cleft affected tissue." (PMID 37733420, 2022). "In the unilateral cleft lip group epithelium, the median number of BARX1 positive epitheliocytes was no positive cells and no BARX1 positive epitheliocytes were found within any slide of the unilateral cleft lip tissue group." (PMID 37733420, 2022). "The exact mechanisms of BARX1 and DLX4 interaction within bilateral cleft lip affected tissue remain relatively unclear but characteristics and correlations between these factors could imply their possible role in bilateral cleft lip pathogenetic mechanisms." (PMID 37733420, 2022). "The median number of BARX1 immunopositive structures in the connective tissues of the bilateral cleft lip group was few to moderate (+/++) and it ranged from no BARX1 positive structures to few to moderate (+/++) positive structures." (PMID 37733420, 2022). "The median number of BARX1 positive epitheliocytes in the bilateral cleft lip tissue group was no positive cells and no BARX1 positive epitheliocytes were found in any slide of the bilateral cleft lip affected tissue group." (PMID 37733420, 2022). "Interestingly, our study revealed that there were statistically significant negative correlations in the bilateral cleft lip tissue which were notified between BARX1 in the connective tissue and MSX2 in the connective tissue and between BARX1 in the connective tissue and DLX4 in the epithelium." (PMID 37733420, 2022). "Interestingly the presence of a statistically significant negative correlation between BARX1 and MSX2 positive structures in bilateral cleft lip affected connective tissue could possibly indicate a disruption of this specific regulatory mechanisms." (PMID 37733420, 2022).
craniofacial clefts (1 paper, 2022). "BARX1 has been previously associated with the formation of craniofacial clefts in humans." (PMID 37733420, 2022). "Some of these proteins like Homeobox Protein BarH-like 1 (BARX1), Distal-Less Homeobox 4 (DLX4), Forkhead Box E1 (FOXE1), Homeobox Protein Hox-B3 (HOXB3), and Muscle Segment Homeobox 2 (MSX2) have been associated with the formation of craniofacial clefts." (PMID 37733420, 2022).
esophageal squamous cell carcinoma (1 paper, 2023). Esophageal squamous cell carcinoma (ESCC) is a type of esophageal carcinoma (EC) that can affect any part of the esophagus, but is usually located in the upper or middle third. "For instance, the BARX1 variant rs11789015 (A>G), which is associated with decreased expression of BARX1 mRNA and protein, confers a decreased risk of esophageal squamous cell carcinoma (ESCC)." (PMID 37587140, 2023).
gastric cancer (1 paper, 2017). A primary or metastatic malignant neoplasm involving the stomach. "Furthermore, over-expression of Barx1 in gastric cancer cells reduced cell proliferation." (PMID 29069753, 2017).
Hernia (1 paper, 2022). "Evidence for shared susceptibility was further provided at nine loci including 2p21 (THADA), 3p14.3 (ERC2), 3p13 FOXP1, 4q34.1 (HAND-AS1), 5p15.33 (CEP72), 7p15.2 (LOC646588), 7q33 (CALD1) and 9q22.31 (BARX1) of which eight were previously discovered on individual hernia GWAS analyses." (PMID 36584111, 2022).
lung carcinoma (1 paper, 2023). "The results showed that the relative expression level of BARX1 mRNA in lung cancer tissues increased by about tenfold compared to matched normal adjacent tissues." (PMID 37587140, 2023). "The results suggest that the knockdown of BARX1 inhibits lung cancer progression in mice due to the downregulation of the downstream master oncogenes." (PMID 37587140, 2023). "Taken together with the results of database analyses and our expression assays of lung cancer tissues from patients, we conclude that BARX1 is upregulated in NSCLC tissues and NSCLC cell lines." (PMID 37587140, 2023). "Why BARX1 expression promotes, but BARX1 knockdown inhibits cell proliferation, migration and invasion of lung cancer cells?" (PMID 37587140, 2023). "Here, we have identified BARX1 as a common DEG overexpressed in lung cancer LUSC and LUAD." (PMID 37587140, 2023). "Further, we examined the expression levels of BARX1 mRNA and protein in lung cancer tissues from 23 patients with LUAD, LUSC and lung cancer cell lines by RT-qPCR or Western blotting." (PMID 37587140, 2023). "Considering the functional characteristics of CDC20, CDC45, TRIM37 and MMP9, it is not surprising that BARX1 promotes cellular proliferation, migration and invasion of lung cancer cells by transactivating CDC20, CDC45, TRIM37 and MMP-9 expression." (PMID 37587140, 2023). "We therefore conclude that BARX1 transactivates CDC20, CDC45, TRIM37 and MMP-9 genes, thereby promoting cellular proliferation, migration and invasion of lung cancer cells due to the functional roles of these genes in cell-cycle progression, DNA synthesis and their association with carcinogenesis." (PMID 37587140, 2023). "Likewise, the relative expression levels of BARX1 mRNA in A549, H157 and GLC-82 lung cancer cells were significantly increased compared to noncancer BEAS-2B cell." (PMID 37587140, 2023).
lung squamous cell carcinoma (1 paper, 2023). "In this study, we identified BARX1 as a common differentially expressed gene in lung squamous cell carcinoma and adenocarcinoma." (PMID 37587140, 2023).
Obesity (1 paper, 2017). Accumulation of substantial excess body fat. "Of these GPGE association results, BARX1, ZNF169 and FAR1 were all significant in brain regions, which is consistent with a popular hypothesis that the central nervous system regulation of energy balance plays a major role in the development of obesity." (PMID 28417008, 2017).
cancer (8 papers, 2016 to 2023). A tumor composed of atypical neoplastic, often pleomorphic cells that invade other tissues. "Moreover, the gene set enrichment analysis (GSEA) was used to identify the enriched cancer hallmark pathways, and the curves showed the top enrichment pathways for BARX1 and DLX4." (PMID 34124141, 2021). "Dysregulation of Barx homeobox 1 (BARX1) expression is involved in various cancers, but its function and mechanism in the process of OS are undefined." (PMID 36927457, 2023). "Then we investigated the effects of BARX1 knockdown on cancer cell growth and proliferation using these cells." (PMID 37587140, 2023). "The expression of KHDRBS2 and MYOZ1 was downregulated in the LUAD cancer samples compared with that in the para-tumor normal samples, whereas the expression of BARX1, ENTPD2, and GFRA3 was upregulated in LUAD cancer tissues." (PMID 36353226, 2022). "Functional experiments were conducted to verify the cancer-promoting effect of BARX homeobox 1 (BARX1) and distal-less homeobox 4 (DLX4) in ccRCC, and Western blot was performed to explore their downstream pathways." (PMID 34124141, 2021). "Other mRNAs such as BARX1, EIF3D, PPP1R7, and HSD17B1 are also known to be associated with different cancers or other diseases." (PMID 29270229, 2017). "PITX2, HOXC13, and BARX1 act as transcription factors, and have been widely investigated in cancers." (PMID 26771237, 2016). "The GSVA analysis of cancer hallmarks revealed that the high expression of BARX1 might trigger unfolded protein response, MYC target, and oxidative phosphorylation, and suppress apoptosis, IL6–JAK–STAT3 signaling, and inflammatory response." (PMID 36353226, 2022). "Recent evidence showed that BARX1 also participated in cancer progression." (PMID 34124141, 2021). "To study whether MGAT5 and MMP9 are required for Barx1-mediated cancer cell invasion and metastasis, we reduced the expression of MGAT5 and MMP9 in SMMC7721-shBarx1 cells with shRNA knockdown." (PMID 29069753, 2017). "However, less is known about the cancer-promoting mechanism of BARX1, and the mechanism of BARX1 dysregulation during carcinogenesis has not been reported so far." (PMID 37587140, 2023).
tumor (4 papers, 2017 to 2023). "The IF assay indicated that BARX1 was overexpressed and associated with HSPA6 overexpression in OS tumour tissues, which revealed the regulatory effect of BARX1 on HSPA6 from a clinical perspective." (PMID 36927457, 2023). "Then, BARX1 mRNA levels were measured in the tumour and adjacent tissues using RT-PCR; the results indicated significant overexpression of BARX1 in the tumour tissue compared with the adjacent tissue." (PMID 36927457, 2023). "The descrambled shRNA (ShControl) and BARX1 shRNA (shBARX1#1) transfected A549 cells were subcutaneously inoculated into nude mice, respectively, followed by measuring tumor volume weekly." (PMID 37587140, 2023). "Increasing evidence shows that BARX1, as a transcription factor, is a two-way regulator of tumour diseases: it can not only promote but also inhibit tumour occurrence and progression." (PMID 36927457, 2023). "The functional interplay was further confirmed by the in vivo tumor xenograft experiment, which showed that BARX1 overexpression promoted tumor progression, and importantly, ZFP36 significantly attenuates BARX1-mediated tumor progression in vivo." (PMID 37587140, 2023). "The attractive attention of the BARX1 oncogenic role has begun only in recent years, based on the identification of DEGs from tumor tissues and matched normal adjacent tissues." (PMID 37587140, 2023). "BARX1 was found to be significantly overexpressed in OS tumour tissue compared with adjacent normal tissue." (PMID 36927457, 2023). "A dual immunofluorescence labelling assay provided further evidence that BARX1 was overexpressed and associated with HSPA6 overexpression in OS tumour tissue." (PMID 36927457, 2023). "Low Barx1 expression is correlated with higher tumor-nodule-metastasis stage and indicates poor prognosis." (PMID 29069753, 2017). "In 40 paired HCC tissues, the mRNA levels of Barx1 are significantly decreased in HCC tissues as compared to adjacent non-tumor tissues and normal liver tissues." (PMID 29069753, 2017). "In summary, we report a novel tumor suppressor function of Barx1, which is frequently down-regulated in human HCC tissues." (PMID 29069753, 2017). "Low expression of Barx1 is significantly correlated with multiple tumor numbers, maximum tumor size, poor tumor differentiation, and a higher tumor-nodule-metastasis (TNM) stage." (PMID 29069753, 2017). "BARX1 regulates the proliferation and metastasis of many tumours." (PMID 36927457, 2023). "Low expression of Barx1 positively correlates with aggressive tumor progression and poor survival." (PMID 29069753, 2017). "In addition, the expression of BARX1 was closely related to tumour size, TNM stage, and metastasis." (PMID 36927457, 2023). "However, enforced BARX1 expression in gastric cancer can inhibit tumour proliferation." (PMID 36927457, 2023). "We demonstrated that BARX1 was upregulated and functioned as an oncogene, whereas ZFP36 was downregulated and acted as a suppressor in NSCLC cell lines and clinical tumor tissues." (PMID 37587140, 2023). "The expression levels of ENTPD2, BARX1, and GFRA3 were higher in LUAD tumor samples than in normal para-tumor samples." (PMID 36353226, 2022).
BARX1 also shares sentences with these, for which no sentence is quoted: esophageal adenocarcinoma (5 papers); Barrett esophagus (2); diabetes (2); adenocarcinoma (1); asthma (1); breast carcinoma (1); cardiomyopathies (1); endometrial carcinoma (1); inflammatory bowel disease (1); ischemic stroke (1); neuroblastoma (1); orofacial cleft (1); osteosarcoma (1); ovarian carcinoma (1); renal carcinoma (1); soft tissue sarcoma (1); type 2 diabetes mellitus (1).